TAF1 (TATA-box binding protein associated factor 1)
Description:
The TFIID basal transcription factor complex plays a major role in the initiation of RNA polymerase II (Pol II)-dependent transcription. TFIID recognizes and binds promoters with or without a TATA box via its subunit TBP, a TATA-box-binding protein, and promotes assembly of the pre-initiation complex (PIC). The TFIID complex consists of TBP and TBP-associated factors (TAFs), including TAF1, TAF2, TAF3, TAF4, TAF5, TAF6, TAF7, TAF8, TAF9, TAF10, TAF11, TAF12 and TAF13. TAF1 is the largest component and core scaffold of the TFIID complex, involved in nucleating complex assembly. TAF1 forms a promoter DNA binding subcomplex of TFIID, together with TAF7 and TAF2. Contains novel N- and C-terminal Ser/Thr kinase domains which can autophosphorylate or transphosphorylate other transcription factors. Phosphorylates GTF2A1 and GTF2F1 on Ser residues. Possesses DNA-binding activity. Essential for progression of the G1 phase of the cell cycle. Exhibits histone acetyltransferase activity towards histones H3 and H4.
Synonyms: p250; TAF(II)250; TAFII-250; TAFII250; BA2R; CCG1; CCGS; TAF2A; NSCL2; KAT4; DYT3/TAF1; DYT3; MRXS33; N-TAF1; OF; XDP
Tractability: Small molecule: a structure with a bound ligand is known; a high-quality ligand is known; it has a binding pocket of medium quality. PROTAC: UniProt records ubiquitination sites on it; ubiquitination databases record sites on it; its protein half-life has been measured; a small molecule that binds it is known.
Target class: Enzyme
Chemical probes: BAY-299 (high quality), TAF1-compound 31 (high quality)
Gene: Protein-coding gene on chromosome X (71,366,131 to 71,532,374, forward strand). Ensembl gene ENSG00000147133.
Subcellular location: Nucleus
Subcellular location (Human Protein Atlas): Nucleoplasm
Pathways (Reactome):
Gene expression (Transcription): RNA Polymerase II Pre-transcription Events; RNA Polymerase II Promoter Escape; RNA Polymerase II Transcription Initiation; RNA Polymerase II Transcription Initiation And Promoter Clearance; RNA Polymerase II Transcription Pre-Initiation And Promoter Opening
Disease: HIV Transcription Initiation; RNA Polymerase II HIV Promoter Escape; Transcription of the HIV genome
Gene Ontology:
Molecular function: acetyl-CoA binding; histone acetyltransferase activity; histone H3K27me3 reader activity; histone H4K16ac reader activity; histone reader activity; kinase activity; nuclear receptor binding; protein binding; protein heterodimerization activity; protein kinase activity; protein serine/threonine kinase activity; protein-lysine-acetyltransferase activity; RNA polymerase I general transcription initiation factor activity; RNA polymerase II core promoter sequence-specific DNA binding; RNA polymerase II general transcription initiation factor activity; RNA polymerase II general transcription initiation factor binding; RNA polymerase II-specific DNA-binding transcription factor binding; TBP-class protein binding; transcription regulator inhibitor activity; ubiquitin conjugating enzyme activity; sequence-specific DNA binding; DNA binding; protein serine kinase activity
Biological process: cellular response to ATP; cellular response to UV; DNA damage response; midbrain development; mRNA transcription by RNA polymerase II; negative regulation of gene expression; negative regulation of protein autoubiquitination; negative regulation of transcription by RNA polymerase II; negative regulation of ubiquitin-dependent protein catabolic process; positive regulation of androgen receptor signaling pathway; positive regulation of proteasomal ubiquitin-dependent protein catabolic process; positive regulation of transcription by RNA polymerase II; positive regulation of transcription initiation by RNA polymerase II; protein polyubiquitination; protein stabilization; RNA polymerase II preinitiation complex assembly; transcription by RNA polymerase II; transcription initiation at RNA polymerase I promoter; transcription initiation at RNA polymerase II promoter; ubiquitin-dependent protein catabolic process; protein autophosphorylation; regulation of cell cycle G1/S phase transition; chromatin organization; and 2 more
Cellular component: chromatin; MLL1 complex; nucleolus; nucleoplasm; nucleus; transcription factor TFIID complex; transcription regulator complex
Homologues: Orthologues: chimpanzee TAF1 (99% identical), macaque TAF1 (99% identical), rat Taf1 (97% identical), mouse Taf1 (96% identical), dog TAF1 (96% identical), tropical clawed frog taf1 (85% identical), zebrafish taf1 (80% identical), Drosophila melanogaster Taf1 (51% identical), Caenorhabditis elegans taf-1 (35% identical). Paralogues in human: TAF1L (90% identical).
Diseases named in the same sentence as TAF1 in open-access papers:
TAF1 is named in the same sentence as 69 diseases in open-access papers, as found by Europe PMC text mining. Sharing a sentence is not in itself a finding about the gene and the disease. The quoted sentences say what the papers report.
X-linked dystonia-parkinsonism (30 papers, 2019 to 2026). X-linked dystonia-parkinsonism (XDP) is a neurodegenerative movement disorder characterized by adult-onset parkinsonism that is frequently accompanied by focal dystonia, which becomes generalized over time, and that has a highly variable clinical course. "An example is a 2.6 kb SVA insertion within intron 32 of the TAF1 gene, which is causative of X-linked dystonia-parkinsonism (XDP) and significantly reduces TAF1 mRNA expression in the caudate nucleus of affected patients." (PMID 41155689, 2025). "The Taf1 gene is located on the X chromosome, andits variants are associated with X-linked dystonia-parkinsonism (XDP), adisorder found exclusively in patients of Filipino ancestry." (PMID 39958699, 2024). "TAF1 has also been linked to X-linked dystonia parkinsonism, with an alternatively spliced transcript of TAF1 discovered in neurons." (PMID 37746814, 2023). "X-linked dystonia-parkinsonism (XDP) is a progressive adult-onset neurodegenerative disorder caused by insertion of a SINE-VNTR-Alu (SVA) retrotransposon in the TAF1 gene." (PMID 35395816, 2022). "One prominent example is the TE SINE-VNTR-Alu (SVA) insertion in intron 32 of the Transcription initiation factor TFIID subunit 1 (TAF1) gene, which is causative of X-Linked Dystonia Parkinsonism (XDP)." (PMID 33020390, 2020). "X-linked dystonia parkinsonism (XDP or “Lubag”) is associated with a SINE-VNTR-Alu retrotransposon insertion within an intron of the TATA box-binding protein–associated factor 1 (TAF1) gene." (PMID 33488508, 2020). "As an outstanding example, an unbiased de novo assembly using LRS (SMRT and synthetic longs reads with 10× Genomics) was important for the identification of SINE-VNTR-Alu insertion in TAF1, a newly discovered gene for X-linked Dystonia Parkinsonism." (PMID 31134132, 2019). "Second, insertion of an SVA-type retrotransposon in a noncoding region of TAF1, that results in abnormal splicing and reduced expression of TAF1 in patient-derived NSCs, is associated with X-linked dystonia parkinsonism." (PMID 30948355, 2019). "A non-coding 2.6 kb insertion of a SINE-VNTR-Alu (SVA)-type retrotransposon in intron 328 of TAF1 causes the neurological disorder X-linked dystonia-parkinsonism (XDP; MIM: 313650)." (PMID 31341187, 2019). "While we limited our analysis to eight SVA within the MHC genomic region, it is noteworthy that there are many SVAs in other genomic regions that are strongly linked to PD, including the SVA insertion within the TAF1 gene that is associated with X-linked dystonia parkinsonism." (PMID 38590523, 2024). "Mutations to the TAF1 gene cause X-linked dystonia parkinsonism and X-linked syndromic intellectual development disorder-33; however, the specific mechanisms by which TAF1 mutations drive these diseases are unknown." (PMID 35625613, 2022). "Besides, recent studies have finally confirmed that X-linked Dystonia-Parkinsonism (XDP) was caused by SINE-VNTR-Alu (SVA) retrotransposon insertion in intron 32 of the TAF1 gene." (PMID 35464305, 2022). "The genetic mechanism underlying the neurodegenerative movement disorder X-linked dystonia-parkinsonism (XDP) involves a retrotransposon insertion within the TAF1 gene." (PMID 42102821, 2026). "X-linked dystonia-parkinsonism (XDP) is a rare neurodegenerative disease caused by mutations in the TAF1 (TATA-binding protein-associated factor 1) gene in the Xq13.1 region of the X chromosome." (PMID 39444378, 2024). "Mutations in the TAF1 gene, which is located on the X chromosome, have been associated with X-linked dystonia-parkinsonism (XDP)." (PMID 37296608, 2023). "Another rare adult-onset condition is X-linked dystonia-parkinsonism (XDP) caused by a founder mutation present in the Philippines that is a ~2.6kb SINE-VNTR-Alu (SVA)-type retrotransposon insertion in intron 32 of the TAF1 gene." (PMID 34360863, 2021).
X-linked dystonia-parkinsonism (continued). "X-linked dystonia-parkinsonism (XDP) is an adult-onset neurodegenerative movement disorder, caused by a founder retrotransposon insertion in an intron of the TAF1 gene." (PMID 38835428, 2021). "CRISPR/Cas9 has also been used to treat the neurodegenerative disease X-linked dystonia-parkinsonism (XDP) by excising the SINE-VNTR-Alu (SVA) retrotransposition in intron 32 of the TAF1 gene in multiple pluripotent stem cell-derived neuronal lineages." (PMID 32760425, 2020). "TAF1 is a gene located on the X chromosome which is known to cause X-linked syndromic mental retardation-33 (MRXS33) and X-linked Dystonia-Parkinsonism (XDP)." (PMID 35464305, 2022). "X-linked dystonia-parkinsonism (XDP), also referred to as Lubag, is a movement disorder initially described in Filipino males, caused by the insertion of a SINE-VNTR-Alu (SVA)-type retrotransposon in intron 32 of the TAF1 gene." (PMID 35328025, 2022). "For example, X-Linked Dystonia-Parkinsonism (XDP), is a progressive neurodegenerative condition which is thought to be caused by a polymorphic SVA insertion in the 32nd intron of the TAF1 gene." (PMID 31783611, 2019).
Parkinsonism (19 papers, 2007 to 2026). Characteristic neurologic anomaly resulting from degeneration of dopamine-generating cells in the substantia nigra, a region of the midbrain, characterized clinically by shaking, rigidity, slowness of movement and difficulty with walking and gait. "TAF1 is dysregulated in X-linked dystonia–parkinsonism and congenital mutations in the gene are causative for neurodevelopmental phenotypes; TAF1 dysfunction is also associated with cardiac anomalies and cancer." (PMID 39323550, 2024). "Human heterozygous female carriers of TAF1 variants demonstrate a spectrum of phenotypes from asymptomatic to dystonia–parkinsonism features." (PMID 38804708, 2024). "TAF1 missense variants in human males cause X-linked intellectual disability, a neurodevelopmental disorder, and TAF1 is dysregulated in X-linked dystonia–parkinsonism, a neurodegenerative disorder." (PMID 38804708, 2024). "Expansions of this SVA-embedded repeat in an intron of the transcription factor IID (TAF1) gene have been associated with functional impact on TAF1, and earlier onset of X-linked dystonia parkinsonism in patients inheriting the insertion." (PMID 37823611, 2023). "For example, the insertion of an SVA element into an intron of the TATA box-binding protein-associated factor 1 (TAF1) gene causes X-linked dystonia with parkinsonism (XDP), a movement disorder endemic to the Philippines." (PMID 35269693, 2022). "The most remarkable example is the presence of an SVA insertion in an intron of the TAF1 gene causing the decreased expression of TAF1 by intron retention, leading to X-linked dystonia-parkinsonism." (PMID 34204806, 2021). "Finally, JUN is up-regulated in post-mortem brains of schizophrenia patients whereas the neuro-specific expression of TAF1 has been related to another neurological disorder: X-linked dystonia-parkinsonism." (PMID 17849003, 2007). "The genetic markers of Parkinson’s disease BCL2, TBP,and TAF1 exert greater regulatory influence on acylcarnitinemetabolism enzymes, while PARP1 equally affects enzymesinvolved in both amino acid and acylcarnitine metabolism." (PMID 39944797, 2024). "TAF1 and DPM2 provide potential clues about parkinsonism and increased creatine phosphokinase in neuroleptic malignant syndrome, while abnormalities in RALGPS1 suggest links to both anti-NMDAR antibody encephalitis and the SHANK3 gene, which is known to predispose to catatonia." (PMID 40400398, 2025). "Parkinsonism genetic panel was negative and whole exome sequencing (WES) revealed a variant of uncertain significance in the TAF1 gene." (PMID 34716756, 2021). "XDP has been reported exclusively in patients of Filipino origin who manifest with adult-onset dystonia–parkinsonism and who all carry the founder ~ 2.6 kb SVA (short interspersed nuclear element, variable number of tandem repeats, and Alu composite) retrotransposon insertion in the TAF1 gene." (PMID 33876307, 2021).
Dystonia (15 papers, 2013 to 2025). An abnormally increased muscular tone that causes fixed abnormal postures. "Reduced neuronal expression of TAF1 is linked to a form of dystonia-parkinsonism known as Lubag or DYT3." (PMID 23849371, 2013). "DYT/PARK TAF1 differs from the previous mentioned strains for the age of onset, body distribution of dystonia, and neuroimaging." (PMID 35887948, 2022). "Other genes found to be associated with isolated or combined dystonia include ANO3 (DYT24), TUBB4A (DYT4), GCH1 (DYT5a), TH (DYT5b), TAF1 (DYT3), PRKRA (DYT16), ATP1A3 (DYT12), SGCE (DYT11), KCTD17, and CACNA1A." (PMID 33051750, 2021). "In particular, five genes linked to dystonia appear to be involved upstream or downstream of DP-1 in the G1-S checkpoint pathway (ATM, CIZ1, TOR1A, THAP1 and TAF1)." (PMID 23849371, 2013). "Among the primary monogenic dystonias, XDP has been identified as a transcriptional dysregulation syndrome with impaired expression of the TAF1 (TATA box-binding protein associated factor 1) gene, which is a critical component of the cellular transcription machinery." (PMID 28672841, 2017). "Moreover, other dystonia-associated proteins including THAP1, TAF1, ATM, and Gα(olf), contribute to the G1/S checkpoint pathway." (PMID 24936516, 2014). "This form of combined dystonia begins in early to late adulthood and, contrary to DYT/PARK-GCH1 that begins with foot dystonia and then progress cranially, DYT/PARK TAF1 involves mainly the upper body, with characteristic jaw opening dystonia and bulbar involvement." (PMID 35887948, 2022).
glioma (7 papers, 2020 to 2025). A benign or malignant brain and spinal cord tumor that arises from glial cells (astrocytes, oligodendrocytes, ependymal cells). "For example, lncRNA LINC00319 regulates glioma development through directly binding to TATA-box binding protein-associated factor 1 (TAF1)." (PMID 38730506, 2024). "lncRNA FOXD2-AS1, TATA-Box binding protein-associated factor 1 (TAF-1), and Notch receptor 1 (NOTCH1) were found to be significantly upregulated in glioma tissues and GSCs." (PMID 38967893, 2024). "TAF1 overexpression has been reported in various cancers, including leukemia, non-small-cell lung cancer, and glioma, where it serves as an oncogenic driver." (PMID 39765756, 2024). "Then, we quantified the expression of lncRNA FOXD2‐AS1, TATA‐box binding protein associated factor 1 (TAF‐1) and NOTCH1 in glioma tissues and GSCs, as well as the expression of GSC stem markers, OCT4, SOX2, Nanog, Nestin and CD133 in GSCs." (PMID 35419917, 2022). "Mechanistically, lncRNA FOXD2‐AS1 elevation promoted glioma in vivo by activating the NOTCH signalling pathway via TAF‐1 upregulation." (PMID 35419917, 2022). "In our study, we aimed to explore the specific role of lncRNA FOXD2‐AS1 in the proliferation and differentiation of GSCs along with the relationship between lncRNA FOXD2‐AS1/TAF‐1/NOTCH1 signalling pathway in glioma." (PMID 35419917, 2022). "TAF‐1 expression was found to be higher in glioma tissues than in normal tissues." (PMID 35419917, 2022). "As previously reported, LINC00319 directly binds to TAF‐1 and further regulates HMGA2 in gliomas, leading us to hypothesize that lncRNA FOXD2‐AS1 is involved in glioma via TAF‐1 and the NOTCH signalling pathway." (PMID 35419917, 2022). "To better understand the specific mechanism underlying the regulatory role of lncRNA FOXD2‐AS1 in glioma cells, we performed a series of assays demonstrating that lncRNA FOXD2‐AS1 upregulation led to elevated NOTCH1 expression by recruiting TAF‐1 to the NOTCH1 promoter region." (PMID 35419917, 2022). "FOXD2-AS1 promotes glioma progression by enhancing stemness and proliferation in glioma stem cells (GSCs) through the activation of the NOTCH signaling pathway via TAF-1 upregulation." (PMID 40909272, 2025). "FOXD2-AS1 overexpression recruits TAF-1 to the promoter region of NOTCH1, resulting in upregulation of NOTCH1 and promotion of the stemness of gliomas." (PMID 38967893, 2024). "Transcripts of VV-GMCSF-Lact-infected glioma and NB cells that directly correlate with CD50 are enriched with mRNAs controlled by transcription factors ATF2, BRCA1, CREB1, ELF1, TAF1, UBTF, and YY1." (PMID 37998351, 2023). "LncRNA FOXD2‐AS1, TAF‐1 and NOTCH1 were found to be elevated in glioma tissues and GSCs, and silencing lncRNA FOXD2‐AS1 inhibited stemness and proliferation, while promoting apoptosis and differentiation of GSCs." (PMID 35419917, 2022). "The interaction of lncRNA FOXD2‐AS1 and TAF‐1 with NOTCH1 was found based on the LncMAP database, and TAF‐1 was initially predicted to be highly expressed in glioma according to the GEPIA website." (PMID 35419917, 2022). "The top five scored genes (TAF1, TAFL1, CBL, CCNT1, and RMNT) were further analyzed in the glioma tissues samples in the CGGA database." (PMID 32322592, 2020). "Further study has found that LinC00319 can directly bind to TATA box binding protein related factor 1 (TAF1) and further regulate HMGA2 to promote glioma cell proliferation, accelerate cell cycle, and inhibit glioma cell apoptosis, providing new ideas for molecular targeted therapy of glioma." (PMID 38967893, 2024).